MCM5 (minichromosome maintenance complex component 5)
Diseases named in the same sentence as MCM5 in open-access papers (continued):
Sharing a sentence is not in itself a finding about the gene and the disease.
infection (3 papers, 2012 to 2024). The state of being infected such as from the introduction of a foreign agent such as serum, vaccine, antigenic substance or organism. "Furthermore, seven genes (CDK1, TYMS, MCM5, KIF11, CCNB2, MAD2L1, and MCM4) have been identified as core hub genes involved in cell-cycle regulation, potentially serving as mediators in the pathogenesis triggered by NN1172 infection within the thymus." (PMID 38362295, 2024).
liver (2 papers, 2010 to 2022). "An injection of mCherry mRNA didn’t lead to liver bifida but heat-shock induced overexpression of MCM5, resulting in liver bifida similar to the phenotype seen in embryos injected with MCM5 mRNA." (PMID 35204787, 2022).
adenocarcinoma (1 paper, 2007). A common cancer characterized by the presence of malignant glandular cells. "Within the adenocarcinomas only, MCM-5 (but not MCM-2) protein expression was also related to the histologic type (Kruskal–Wallis ANOVA, P=0.0349), the highest levels of immunoreactivity being recorded in poorly differentiated and nonspecified categories." (PMID 17940502, 2007). "Within both the LMP and adenocarcinoma groups MCM-5 (but not MCM-2)-positive cells tended to outnumber Ki-67-positive cells (Wilcoxon's signed rank paired test P=0.0300 and 0.0206, respectively)." (PMID 17940502, 2007).
MCM5 also shares sentences with these, for which no sentence is quoted: cervical dysplasia (2 papers); endometrial cancer (2); gastric adenocarcinoma (2); glioblastoma (2); lung squamous cell carcinoma (2); and Muscular Disorder (1); biliary tract cancer (1); cervical (1); Diabetes (1); dwarfism (1); Fanconi anemia (1); Gorlin syndrome (1); leiomyosarcoma (1); liposarcoma (1); medulloblastoma (1); mucinous tumours (1); nasopharyngeal carcinoma (1); non-small cell lung carcinoma (1); ovarian serous cystadenocarcinoma (1); pleomorphic liposarcoma (1); prion disease (1); rheumatoid arthritis (1); round cell liposarcoma (1); salivary gland cancer (1); tongue cancer (1); urothelial carcinoma (1); uterine corpus endometrioid carcinoma (1).